RNU6-823P (RNA, U6 small nuclear 823, pseudogene)
Gene: Small nuclear RNA gene on chromosome 3 (128,141,875 to 128,141,977, reverse strand). Ensembl gene ENSG00000212344.
Homologues: Orthologues: chimpanzee U6 (100% identical), macaque U6 (95% identical), dog U6 (73% identical), guinea pig U6 (69% identical), dog U6 (67% identical), rabbit U6 (66% identical). Paralogues in human: RNU6-1024P (80% identical), RNU6-24P (79% identical), RNU6-1060P (78% identical), RNU6-1088P (78% identical), RNU6-1114P (78% identical), RNU6-116P (78% identical), RNU6-1175P (78% identical), RNU6-11P (78% identical), RNU6-1257P (78% identical), RNU6-1309P (78% identical), RNU6-279P (78% identical), RNU6-317P (78% identical), and 1284 more.